CD200 (CD200 molecule)
Diseases named in the same sentence as CD200 in open-access papers (continued):
Sharing a sentence is not in itself a finding about the gene and the disease.
tumor (continued). "We postulated that the presence of immune checkpoint proteins in the tumor lysate may compromise the efficacy of this therapy and that treatment with CD200 peptide ligands would modulate the effects of any CD200 checkpoint protein in the lysate vaccine." (PMID 30682795, 2019). "Our current data also disclose a mechanism by which CD200:CD200R1 affects tumor progression and may strengthen the feasibility of targeting CD200 or CD200R1 as anticancer strategy." (PMID 30800162, 2019). "Upon interaction with its receptor CD200R1, CD200 triggers an immunosuppressive signal, leading to macrophage inhibition, regulatory T-cell induction, cytokine profile switching from Th1 to Th2, and eventually, inhibition of tumor-specific T-cell immunity." (PMID 31627350, 2019). "This is a first-in-human phase I trial to evaluate the safety, pharmacokinetics (PK), pharmacodynamic (PD), and anti-tumor activity of CD200 blockade with samalizumab in patients with CLL and MM, and to identify the maximum tolerated dose (MTD) and dose-limiting toxicity (DLT) of samalizumab." (PMID 31443741, 2019). "Although CD200 triggers the signaling inside tumor cells, the mechanisms contributing to treatment resistance and tumor initiation beyond its established immune-regulatory functions remain unclear." (PMID 31627350, 2019). "We showed that expression of CD200 on either host or tumor cells increased tumor burden." (PMID 30653571, 2019). "The augmented CD200 expression not only attenuates antigen-specific Th1 cytokines such as IFNγ and TNFα production but also direct them to acquire Th2 phenotype (expression of IL-4/IL-10 cytokines in viral and tumor pathogenesis)." (PMID 29915577, 2018). "Due to the important role of CD200 in regulating tumor microenvironment in this setting, its expression may be of importance also in ENE-positive CRCs." (PMID 30202242, 2018). "In the following studies we explored whether immunotherapy and chemotherapy could be manipulated to enhance tumor resistance, by modulating host and/or tumor CD200 expression, and using metformin as a novel chemotherapeutic." (PMID 28234914, 2017). "Control CD200-/- mice received only surgical resection of tumor." (PMID 28234914, 2017). "While CD200-/- mice were cured of tumor growth using conventional chemotherapy with a combination of paclitaxel and anti-VEGF antibody, this treatment was not affected by anti-CD4 or anti-CD8 treatment, and did not lead to development of any immunity to re-challenge with the same tumor." (PMID 28234914, 2017). "Furthermore, silencing CD200 expression in EMT6siCD200 tumor cells reduced their ability to grow and metastasize in WT animals." (PMID 28234914, 2017). "Enhanced autophagy has been reported to be essential for CD8+ T cell memory cell survival, and this could explain the significant increase in the number of CD8+ cells in the DLN of CD200-/- mice treated with metformin after tumor resection and immunization." (PMID 28234914, 2017). "Thus control EMT6 tumors growing in immunocompetent WT female BALB/c mice reach upwards of 0.7cm3 by day 18 post tumor cell injection, with similar growth in CD200-/- mice." (PMID 28234914, 2017). "Reduced expression of CD200 by EMT6 tumor cells resulted in decreased local tumor growth and metastasis tumor size, which we hypothesized may reflect an enhanced adaptive anti-tumor immune response to EMT6siCD200 cells compared with control EMT6 cells." (PMID 28234914, 2017). "We did note a difference in the ability of EMT6 and EMT6siCD200 tumors to metastasize to DLN in CD200-/- vs WT mice, with even control EMT6 metastasizing less in CD200-/- mice, indicating an importance for both host and tumor CD200 expression in this phenomenon." (PMID 28234914, 2017). "Like CD200, an inhibitory member of the B7 family of T cell co stimulation, expression of another such molecule, B7× (B7-H4) has been reported to influence metastasis using 4T1 tumor cells and B7KO mice." (PMID 25409195, 2014).
tumor (continued). "The first data on a likely anti-CD200 treatment in neoplastic diseases come from hematologic malignancies where it has been demonstrated that CD200 blockade may represent a novel approach to clinical treatment of CLL." (PMID 25013764, 2014). "However, the impact of tumor expression of CD200 on tumor immunity remains poorly understood and the expression of the discussed molecules was not assessed on the Mo-DC of LC patients." (PMID 23632869, 2013). "Since TAMCs are the major lineages of cells expressing CD200R, we hypothesize that tumor expression of CD200 inhibits the functions of TAMCs and thereby affects tumor formation and metastasis." (PMID 22319630, 2012). "Thus, our data establish that tumor expression of CD200 inhibits tumor formation and metastasis via inhibiting CD200R+ myeloid cells." (PMID 22319630, 2012). "In addition, treatment with tumor antigen specific CD4 or CD8 T cells or their combination yielded a significant improvement in survival of CD200 positive tumor bearing mice." (PMID 22319630, 2012). "In addition, treatment with tumor antigen specific CD4 or CD8 T cells or their combination yielded a survival advantage for CD200 positive tumor bearing mice over mice bearing CD200-negative tumors." (PMID 22319630, 2012). "Thus, our data challenge the current paradigm that tumor expression of CD200 promotes tumor progression and metastasis." (PMID 22319630, 2012). "Thus, targeting CD200R1 for breaking CD200/CD200R1 immune tolerance in cancer presents an opportunity to target multiple immune cell populations in addition to T cells in the tumor, such as myeloid and NK cells, which has been shown to be a promising approach in preclinical research." (PMID 39651931, 2025). "Furthermore, CD200 expression on tumor-infiltrating immune cells could help modulate excessive immune activation, thereby reducing tissue damage and maintaining immune homeostasis." (PMID 40075669, 2025). "Noteworthily, the high-risk group indicated lower expression levels of CD200, NRP1, and TNFRSF14, suggesting that tumor cells might evade immune surveillance through inhibiting the function of these immune checkpoint genes, which could subsequently affect patient prognosis." (PMID 40365116, 2025). "Similarly, the inhibition of CD200 reduces tumor growth in syngeneic mouse models." (PMID 39795972, 2024). "In addition to this therapy, one French bulldog also received temozolomide and another received temozolomide plus gene therapy initially but was treated with autologous tumor lysate vaccination and CD200 immune checkpoint inhibition following surgical resection of tumor regrowth." (PMID 39794971, 2024). "Interestingly, BTLA, CD200, IDO1, LAG3, TNFSF14, etc., were overexpressed in the low-risk group, suggesting that low-risk patients may get better treatment outcomes in tumor immunotherapy." (PMID 38169540, 2024). "More recently, using a Cd200 conditional null mouse model, we identified the collagen peptidase Cathepsin K (Ctsk) as a crucial target gene of the Cd200-Cd200r signaling axis in Cd200r+ tumor-infiltrating myeloid lineages, which was required for tumor cell invasion and metastasis." (PMID 36738455, 2023). "In addition, the interaction of CD200 with CD200R is involved in the regulation of tumor immunity." (PMID 37958359, 2023). "Collectively, these studies illustrate a key pro-tumorigenic role for CD200 in directly suppressing T-cell and NK cell anti-tumor function and that blocking the engagement of the CD200-CD200R axis may provide therapeutic benefit to patients with CD200-expressing tumors." (PMID 36738455, 2023). "Second, CD200 expression may be present at early stages of development for certain tumors, whereas, in other lesions, CD200 expression is induced during late-stage progression and only in a sub-set of tumor cells." (PMID 36738455, 2023).
tumor (continued). "Thus, contrary to earlier conclusions, CD200 may have a dichotomous role in differentially regulating tumor growth, progression, and metastasis based on cancer type." (PMID 38137547, 2023). "Some of these alternative mechanisms extend beyond direct suppression of anti-tumor T cell responses and, as such, may not be susceptible to CD200 antibody blockade." (PMID 36738455, 2023). "Therefore, future investigations might profitably focus on tumour models with higher expression of CD200." (PMID 37082107, 2023). "Interestingly, the overexpression of HERV was associated with a significant elevation of immune checkpoint molecule CD200 in both quantitative PCR and RNA-seq analysis suggesting tumor escape mechanism in NB cell lines after incubation in serum-free stem cell medium." (PMID 34026614, 2021). "Finally, besides its expression on Tfh, CD200 was found overexpressed on tumor B cells and could contribute to the induction of the immunosuppressive enzyme indoleamine-2,3 dioxygenase by CD200R-expressing dendritic cells." (PMID 33028033, 2020). "Notably, plasma levels of soluble CD200 correlate with tumor burden and survival in CLL patients." (PMID 30682795, 2019). "In addition to immunosuppression, overexpression of CD200 on tumor cells has been correlated with aggressive tumor progression, greater metastatic potential, and reduced patient survival, which suggests that CD200 is a promising target for cancer immunotherapy." (PMID 31443741, 2019). "Given the ongoing transmission of DFT for at least 20 years, immunohistochemical analysis of archived DFT tissue samples should determine expression levels of CD200 in the tumor microenvironment, and understanding this potential inhibitory pathway could help direct vaccine-development efforts." (PMID 28515726, 2017). "Taken together these results support the hypothesis that CD4+ T cells play an immunoregulatory tumor-promoting role in mice with EMT6 tumors, while CD8+ cells play a protective role in attenuating tumor growth-and that CD200 expression by tumor cells further modulates these effects." (PMID 28234914, 2017). "However, to date any suggestion that CD200R:CD200 influences T cell responses has largely come from tumor studies and it remains largely unknown how CD200R and CD200 are regulated in T cells during infection." (PMID 22496920, 2012). "Since tumor expression of CD200 differentially affect tumor formation in the subcutaneous model versus the lung metastatic model, we hypothesized that the lung and peripheral tumor microenvironment decided the differential susceptibility to CD200-mediated suppression of tumor growth." (PMID 22319630, 2012). "CD200 has been associated with tumour progression and poor prognosis in several cancers and is over-expressed in CRC with markers for CSC, suggesting that tumour-initiating CSC may evade immune system detection through CD200-induced suppression of T-cell-mediated immune responses." (PMID 21339979, 2010). "Targeting the CD200-mediated dormant niche in combination with chemotherapy and immune check point blockade (ICB) significantly eradicated the dormant tumor cells." (PMID 41674835, 2026). "The expression of CD200 and CD200R1 was evaluated by IHC in FFPE archival or baseline tumor biopsy samples collected from study participants." (PMID 39651931, 2025). "Connecting these data with our earlier observations on the role of IFN-γ in promoting dormancy, we found increased CD200 expression in cultured D2A1 and 4T1 tumor cells in response to IFN-γ treatment." (PMID 40568095, 2025). "Tumor metastasis decreases immunoregulatory LEC subsets, such as PD-L1+ subcapsular sinus LECs, while inducing an increase in capillary-like CD200+ HEY1+ LECs." (PMID 41249124, 2025). "Recent studies have observed elevated glycoprotein CD200 (also known as OX-2) mRNA expression in in different types of tumors, with CD200R-expressing myeloid cells present in the tumor microenvironment." (PMID 40075669, 2025).
tumor (continued). "To probe the potential function of CD200 in regulating NK activity, we set up an in vitro co-culture of CD200-overexpressing D2A1 tumor cells with CD200R1Hi NK or CD200R1Hi macrophages as a control." (PMID 40568095, 2025). "Integrated characterization of tumor and immune features, a four-gene prognostic signature comprising CD276, MS4A1, IGFBP1, and CD200 was established." (PMID 41488652, 2025). "The findings demonstrated that cluster 1 has highly expressed immunosuppressive sites such as BTLA, CD200, CD200R1, CD44, HAVCR2, etc. that promote immunosuppression and tumor formation." (PMID 38347320, 2024). "A combination of CD200 targeting with novel immunotherapeutic approaches, including CAR T cells and bispecific antibodies, presents new opportunities in tumor treatment." (PMID 39795972, 2024). "miRNAs have been reported to alter the expression of molecules, e.g., PD-L1, which, like CD200:CD200R, are known members of the checkpoint inhibitor family, which can also modulate host anti-tumor responses." (PMID 38540350, 2024). "The interaction between CD200 and CD200R suppresses the immune activities against tumor cells and allows them to be undetected and, in doing so, to escape from the destructive capability of the immune cells." (PMID 39795972, 2024). "While we have observed CD200 expression on the tumor and stromal cells in the PDAC TME, CD200 has been reported to be expressed on immune populations, such as T cells, B cells, and DCs." (PMID 38619621, 2024). "CD200 binds to its cognitive receptor, CD200R, and the CD200/CD200R interactions regulate the immune tolerance and weaken antitumor immunity within the tumor microenvironment." (PMID 39795972, 2024). "Together, targeting CD200/CD200R is regarded as a promising approach in cancer immunotherapy, although its ability to prevent tumor growth and spread is not fully understood." (PMID 39795972, 2024). "Targeting the CD200/CD200R pathway, either through the use of monoclonal antibodies or peptide inhibitors, has shown to be effective in boosting anti-tumor immune activity." (PMID 36756156, 2023). "The interaction between highly expressed CD200 on cancer cells and CD200R on immune cells protects tumor cells by inhibiting myeloid cells." (PMID 37894750, 2023). "In summary, the CD200/CD200R axis is a multifaceted player in the immune landscape of cancer, with the potential to both promote and inhibit tumor growth." (PMID 38137547, 2023). "CD200 is expressed along with PD-1 and CXCL13 in follicular helper T cells (Tfh) in T cell-derived neoplasm." (PMID 37894750, 2023). "The CD200/CD200R axis plays a complex and bidirectional role in cancer, regulating immune responses and impacting tumor progression." (PMID 38137547, 2023). "Considering CD200/CD200R’s ability to downregulate immune activity and suppress the body’s anti-tumor defenses, this cellular interaction has sparked researchers’ interest as being a key target for immunotherapy." (PMID 36756156, 2023). "Samalizumab (Alexion), a recombinant humanized monoclonal antibody that specifically binds to CD200, has been investigated clinically for patients with CLL and MM, and it resulted in a decreased tumor burden in 60% of patients with CLL." (PMID 37894750, 2023). "However, there is evidence suggesting that CD200 may also contain anti-tumor effects based on its suppression of tumor-promoting inflammation, angiogenesis, expansion of tumor-associated myeloid cells (TAMC), and improvement of the efficacy of anti-PD-1/PD-L1 treatments." (PMID 38137547, 2023). "Immune checkpoint proteins, including Programmed Death 1 (PD-1) and its ligands PD-L1 and PD-L2, Lymphocyte Activation Gene 3 (LAG-3), CD200, Cytotoxic T Lymphocyte Activator 4 (CTLA-4), and CD47, are involved in tumor immunology and benefit tumor growth." (PMID 37626420, 2023). "CD200/CD200R signaling has been posited to facilitate cancer progression through the recruitment and tumor infiltration of regulatory T cells (Tregs)." (PMID 38137547, 2023).
tumor (continued). "Blocking CD200 inhibition of MAPK or PPARγ signaling restored NK cell survival and tumor cell killing, with relevance to many cancer types." (PMID 36074574, 2022). "Since human CD200 peptide induced murine CD200R signaling, we were able to determine the effect of CD200 expression on the inflammatory infiltrate within grafted tumor cells." (PMID 36074574, 2022). "The blockade of anti-CD200 antibody reduced the number of intra-tumoral MDSCs, restricting PDAC tumor growth and significantly enhancing the anti-tumor efficacy of ICB and anti-PD-1 antibody." (PMID 36131911, 2022). "It interacts with the transmembrane glycoprotein CD200, which can be expressed on a variety of cells, including CD4+ and CD8+ T cells and tumor cells." (PMID 33918618, 2021). "Of note, a subpopulation of CD4+ T cells have previously been shown to express CD200R, and CD200+ CLL cells and CD200RCD4+ T cells seem to colocalize in the tumor microenvironment." (PMID 34439393, 2021). "CD200 blockade resulted in a decrease of CLL engraftment in peritoneal cavity and increased number of CD8 T cells, which play a key role in tumor B cell killing." (PMID 33562512, 2021). "Interestingly, in our study, we pointed out the presence of CD200-enriched milieu in FL, and other partners such as monocytes or DC have already been described as contributors to the FL microenvironment by promoting tumor growth through the recruitment of accessory immune cells." (PMID 33028033, 2020). "CD200 imparts an immunoregulatory signal through its receptor, CD200R1, leading to the suppression of tumor specific immunity." (PMID 30800162, 2019). "Tumor growth in each group increased proportionately with CD200 expression and most tumors in the MEER/control group were rejected (tumor-free: 4/5 mice)." (PMID 31627350, 2019). "We previously observed that CD200 overexpression by CD200tg hosts resulted in increased tumor-induced IFN-γ and decreased IL-6 responses further documenting efficiency of CD200fc as CD200 mimetic." (PMID 29721190, 2018). "We subsequently extended these earlier findings to a model in which anti-EMT6 tumor immunity was explored in CD200-/- mice and CD200R-/- receiving immunotherapy (with irradiated tumor cells and CpG as adjuvant) following surgical resection of tumor." (PMID 28234914, 2017). "While complete cure was achieved in CD200R-/- mice with this regimen, in CD200-/- mice the same protocol was able to decrease EMT6 metastasis, but was insufficient for generating a long-lasting anti-tumor immune response." (PMID 28234914, 2017). "A B-cell associated signature distinguished HPV(+) from HPV(−) tumors, and included the DEGs CD200, GGA2, ADAM28, STAG3, SPIB, VCAM1, BCL2 and ICOSLG; the immune signal relative to T-cells was qualitatively similar between TILs of both tumor cohorts." (PMID 27462861, 2016). "Based on their biological roles in the context of cancer, it appears that the inhibition of CD200 and FAT4 would be effective in reducing tumor volume." (PMID 24944582, 2014). "We suggest that CD200/CD200R interactions on myeloid cells expand the myeloid-derived suppressor cell (MDSC) population and that blocking tumor-derived CD200 will enhance the efficacy of immunotherapy." (PMID 25598973, 2014). "The main aim of the present study was to assess the expression of B7H1, B7H4, CD200 and CD200R on CD83+ Mo-DC, pulsed with autologous tumor cell lysates (aTCL), of patients who suffer from LC in comparison to healthy donors (HD)." (PMID 23632869, 2013). "Tumor cells can therefore escape from the immune responses by numerous mechanisms, including the molecule B7H1, B7H4, and CD200 that acts as a potent suppressor of CD200R-expressing immune cells." (PMID 23632869, 2013). "Our data support a model that tumor expression of CD200 inhibits CD200R+ myeloid cells in the tumor microenvironment, which renders the tumor microenvironment more permissive to T cells and confers better tumor destruction." (PMID 22319630, 2012).